MIR548AQ (microRNA 548aq)
Synonyms: hsa-mir-548aq
Gene: MicroRNA gene on chromosome 3 (185,767,847 to 185,767,904, reverse strand). Ensembl gene ENSG00000265470.
Homologues: Orthologues: chimpanzee MIR548AQ (100% identical). Paralogues in human: MIR548P (88% identical), MIR548AZ (84% identical), MIR548S (84% identical), MIR548X (84% identical), MIR548AA1 (83% identical), MIR548F1 (83% identical), MIR548K (83% identical), MIR548O2 (83% identical), MIR548AJ1 (79% identical), MIR548H3 (79% identical), MIR548AH (78% identical), MIR548F3 (78% identical), and 13 more.